RAD51B (RAD51 paralog B)
Diseases named in the same sentence as RAD51B in open-access papers (continued):
Sharing a sentence is not in itself a finding about the gene and the disease.
osteosarcoma (1 paper, 2021). A usually aggressive malignant bone-forming mesenchymal neoplasm, predominantly affecting adolescents and young adults. "Notably, analyses of the osteosarcoma dataset revealed conservation of at least one CRY1 binding site of putative impact on HR factor regulation (RAD51B)." (PMID 33452241, 2021).
prostate tumor (1 paper, 2015). "We have also detected eQTLs for RAD51B within the EuroBATS data only and for RAD23B in normal prostate TCGA data, but not in prostate tumor." (PMID 26025378, 2015).
rectal cancer (1 paper, 2023). A primary or metastatic malignant neoplasm that affects the rectum. "Interestingly, an intron variant of RAD51B rs2189517 has been demonstrated to be associated with rectal cancer risk." (PMID 37858068, 2023).
serous cystadenoma (1 paper, 2023). A serous neoplasm in which the cysts and papillae are lined by a single layer of cells without atypia, architectural complexity or invasion. "Likely pathogenic mutations were observed in RAD51B, the sensor and modulator of DNA damage, in serous cystadenoma." (PMID 37091785, 2023). "Likely pathogenic mutations in RAD51B, a member of the RAD51-XRCC2 (BCDX2) complex in HR, were observed in the serous cystadenoma sample." (PMID 37091785, 2023).
sinonasal carcinoma (1 paper, 2022). "A locus-specific loss of heterozygosity in the PEComa but not in the sinonasal carcinoma was identified, suggesting the causative role of the splice mutation in the PEComa pathogenesis, because we excluded known pathogenetic pathways characteristic to PEComas (TSC1/2, TFE3, RAD51B)." (PMID 35419288, 2022).
thyroid cancer (1 paper, 2025). "A study of a Chinese ethnic population evaluated the association of SNPs in the 3′-UTR double-strand break repair genes RAD51, RAD51B, BRCA1 (rs12516, rs8176318), BRCA2 (rs15869), XRCC4, and XRCC5 with the risk of thyroid cancer in 206 patients with PTC." (PMID 40361383, 2025).
uterine sarcomas (1 paper, 2025). "Clinically, RAD51B fusion uterine sarcomas tend to behave aggressively and are associated with an unfavorable prognosis." (PMID 41463261, 2025). "With the increasing use of next-generation sequencing, recognition of RAD51B-rearranged uterine sarcomas has grown, and they are now regarded as a distinct molecular subgroup of uterine sarcomas with diverse morphologic manifestations but a typically malignant clinical course." (PMID 41463261, 2025). "RAD51B fusion uterine sarcoma is not a morphological diagnosis, but rather a mixture of recently recognized subset of uterine sarcomas characterized by gene fusions involving RAD51B and various partner genes, most commonly HMGA2 or NUDT3." (PMID 41463261, 2025).
cancer (59 papers, 2010 to 2026). A tumor composed of atypical neoplastic, often pleomorphic cells that invade other tissues. "Significantly, a genome-wide analysis of somatic noncoding mutation patterns in cancer has revealed that RAD51B harbors frequent noncoding mutations in promoter and enhancer regions." (PMID 37858068, 2023). "Whilst RAD51C and RAD51D are now established cancer predisposition genes, loss-of-function germline variants in RAD51B have only been reported in individual cases of breast and ovarian cancer." (PMID 34635660, 2021). "To investigate the potential contribution of RAD51B loss-of-function germline variants to cancer predisposition, we analyzed a cohort of 18,087 individuals with cancer whose tumor and blood samples were characterized using MSK-IMPACT." (PMID 34635660, 2021). "The RAD51B gene is implicated in the DNA repair pathway; viral integrations in this gene cause loss of function and have been associated with other types of cancer, like breast, ovary, prostate, and colorectal." (PMID 33810183, 2021). "In contrast to this, monoallelic variants of the RAD51 gene and of five of its paralogs have recently been involved in cancer predisposition: RAD51B, RAD51C, and RAD51D in OC; RAD51, RAD51B, and XRCC2 in BC." (PMID 32046255, 2020). "Our results show that multiple cancer-susceptibility SNPs, namely rs3784099, rs2842347, and rs1314913, are located on RAD51B, a gene whose protein is essential for DNA repair by homologous recombination." (PMID 32850701, 2020). "Pathogenic variants were identified in CHEK2, MUTYH, and RAD51B in four cancer patients, which represented 8.3% of the cohort." (PMID 31780696, 2019). "Overall, haploinsufficiency of RAD51B was shown to induce genomic instability in human cells, suggesting its involvement in cancer predisposition." (PMID 24139550, 2013). "In addition, as an important DNA repair gene, RAD51B also has been identified to be associated with therapy resistance and prognosis of several cancers." (PMID 37858068, 2023). "Mutated RAD51B may facilitate deleterious DNA damage during HR, leading to increased cancer susceptibility." (PMID 36289474, 2022). "• RAD51B splice mutations leading to exon skipping have been associated with cancer." (PMID 34469537, 2021). "Here, we sought to determine whether germline loss-of-function variants in RAD51B confer an increased risk to these cancers, and whether the resulting tumors harbor a therapeutically targetable HRD phenotype." (PMID 34635660, 2021). "Furthermore, RAD51B gene has been identified as a risk factor for prostate, ovarian, breast, head and neck and other cancer types in recent reports." (PMID 29207658, 2017). "Recent studies suggested that common genetic variants of RAD51B may contribute to cancer susceptibility." (PMID 27334422, 2016). "After exclusion criteria were applied, six genes (GBA, ATG10, TRIM27, CD160, ISYNA1, RAD51B) were selected for validating the associations between DNA methylation and BC with MassARRAY EpiTyper assays in validation I (48 sporadic BC cases and 48 matched cancer-free female controls)." (PMID 35812748, 2022). "In addition to providing evidence that RAD51B serves as a cancer predisposition gene, our findings confirm that tumors harboring biallelic inactivation of RAD51B are deficient in HR and are likely to be sensitive to both PARP inhibitors and interstrand crosslinking agents." (PMID 34635660, 2021). "This positive correlation was also observed in 1515 human cancer cell lines across 30 tissue types, suggesting a regulatory relationship between RAD51B and the estrogen-response pathway." (PMID 41318657, 2025).
cancer (continued). "SVs affecting RAD51B, a component of the DNA double-strand break repair response, were also associated with significantly higher levels of TBL in 13 cancer types from the TCGA and in all three cancer types with an SV within RAD51B in the PCAWG." (PMID 40369102, 2025). "WGS data from the Pan-Cancer Analysis of Whole Genomes (PCAWG) dataset of 2,658 whole-cancer genomes across 38 tumour types found the most mutated DNA break repair mechanisms (DBRMs) genes to be FANCA, POLE, PRKDC and RAD51B." (PMID 36289474, 2022). "RAD51B is predominantly intronic (exon:intron bp ratio=0.00208) and ranks lowest when compared to HR and known cancer genes." (PMID 36289474, 2022). "Differential expression of CD160, ISYNA1 and RAD51B has been correlated to the clinical characteristics in various types of cancer." (PMID 35812748, 2022). "In our study, we observed significantly lower methylation of CD160, ISYNA1 and RAD51B in blood DNA of BC patients than that of cancer-free controls in the Chinese population." (PMID 35812748, 2022). "A t(12:14) translocation at the 4th month formed Rad51b-Fbxo34 fusion; Ccnd3 regulates G1/S transition and is frequently dysregulated in many cancer types." (PMID 35869059, 2022). "Since age has impact on DNA methylation patterns, we next evaluated the relationship between the methylation levels of CD160, ISYNA1 and RAD51B and age in 272 sporadic BC cases and 272 cancer-free female controls combining validation I and validation II." (PMID 35812748, 2022). "But the most remarkable pro-cancer RAD52 phenotype is seen in cancer cells deficient in any of the following DNA repair proteins: BRCA1, BRCA2, PALB2, XAB2 or RAD51 paralogs: RAD51B, RAD51C, RAD51D, XRCC2 and XRCC3." (PMID 34887904, 2021). "Gain of MRN complex genes, RAD54B and RAD51B, whose alterations were reported to be involved in cancer progression, was related to poorer overall survival." (PMID 33178606, 2020). "This SNP is located on chromosome 14 on the RAD51B gene, a known cancer gene involved in homologous recombination repair (HRR)." (PMID 32850701, 2020). "RAD51B and XRCC3 polymorphisms have been identified as a risk factor for prostate, ovarian, breast, head and neck and other cancer types." (PMID 27683114, 2016). "Here, we explored the utility of the HR gene Rad51B, Rad51C, Rad51D and Rad52 for transcriptionally targeted therapy of cancer." (PMID 24742710, 2014). "In order to identify alternative promoters with high specificity to cancer cells we examined the tumor specificity of Rad51 paralogs Rad51B, Rad51C, Rad51D and Rad52." (PMID 24742710, 2014). "To identify cancer-specific promoters we first compared the expression levels of Rad51B, Rad51C, Rad51D and Rad52 in a panel of seven normal and seven cancerous cells lines." (PMID 24742710, 2014). "We found several SNPs with nominally significant effects on the correlation of CEB with post-reproductive lifespan; two of them are near EOMES and RAD51B, genes that are related to cancer when under-expressed." (PMID 24481203, 2013). "This revealed an increase in RAD51B, RAD51C and RAD51D paralogue mutations in human cancers." (PMID 42133623, 2026). "In this study, HPV integration sites were found in intron 7 of RAD51B-204 (the main transcript) and its breakage may be promoting progression of cancer." (PMID 37966613, 2023). "Cancer susceptibility in patients with ATM and RAD51B alterations are still evolving with recent studies implicating these genes in a number of cancers; however, their contribution to CRC carcinogenesis at this time is unknown." (PMID 36611031, 2023). "RAD51B plays a vital role in homologous recombinational repair of DNA double-strand breaks to maintain cell genomic stability and is a promising candidate oncogene and biomarker for cancer diagnosis and prognosis." (PMID 35812748, 2022). "Our results suggested that age might be a confounder for the cancer associated aberrant methylation of CD160, ISYNA1 and RAD51B in the blood." (PMID 35812748, 2022).
cancer (continued). "CD160, ISYNA1 and RAD51B have been involved in the development of various types of cancer." (PMID 35812748, 2022). "Other highly mutated HR-related genes, including RAD51B (mutation frequency in patients, 6.1%), ATR (6.1%), ATM (6.1%), PALB2 (6.1%), and BRIP1 (4.9%), have been reported to be capable of affecting the sensitivity of various cancer cells to PARPis." (PMID 35952757, 2022). "The ability of HPV integration to alter expression of nearby human genes (within 500 Kb) has been demonstrated in both OPSCC and UCSCC with recurrent integration sites identified near genes implicated in cancer such as MYC, MYB, PVT1, RAD51B, EMBP1, CD274/PD-L1, and SOX2." (PMID 36139648, 2022). "Three male patients in our cohort carrying a RAD51B loss-of-function variant were affected by malignant tumors, but none were of mammary origin." (PMID 34635660, 2021). "Here, we focused on the human RAD51 paralogs—RAD51B, C, D, XRCC2, 3, and SWSAP1—and explored their known and emerging functions, the challenges in further uncovering their roles, and their association with cancer predisposition." (PMID 30551670, 2018). "RAD51B plays a central role in homologous recombinational repair (HRR) of DNA double‐strand breaks (DSBs), which is important to prevent genomic instability, a hallmark of cancer." (PMID 27334422, 2016). "Furthermore, upregulated expression of RAD51B was observed in gastric precancer and cancer tissues." (PMID 37858068, 2023). "Specifically, the DNA repair genes like RAD51B and RAD18, cancer stem cell marker SOX2 and antiapoptotic genes were significantly up regulated in radiation resistant cells." (PMID 34762666, 2021). "Silencing of RAD51B also resulted in increased sensitivity to olaparib and mitomycin-C, agents that are both known to target HRD cancers." (PMID 34635660, 2021). "HPV integration is most frequently detected in genic regions, most often cancer-related genes, such as oncogenes (e.g., TP63, MYC, ERBB2) or tumor suppressor genes (e.g., BCL2, FANCC, HDAC2, RAD51B, CSMD1) and to a lesser extent in miRNA regions." (PMID 34439243, 2021). "In contrast, RAD51B, XRCC3 and SPRTN were differentially methylated and also clustered closely together in all three cancer types." (PMID 27683114, 2016). "In addition, recurrent breakpoints of SVs targeting cancer genes commonly occurred in frequently deleted regions, e.g., CDKN2A on 9p21.3, MAML2 and ATM on 11q21-22, RAD51B, and TRAF3 on 14q 24-32.3, CYLD and NLRC5 on 16q12.1-13." (PMID 34234122, 2021). "The five classical RAD51 paralogs [RAD51B, RAD51C, RAD51D, XRCC2 and XRCC3] are important components of the homologous recombination pathway that preserves genomic integrity and protects against cancer." (PMID 31584931, 2019). "Frequent HPV integrated into RAD51B might disrupt the DNA repair mechanism, which could partially explain the HPV-rendered genomic dysfunction and chromosome instability in cancers." (PMID 30018982, 2018). "We identified genes from the homologous recombination pathway in the gene lists and cross-validation of all three candidate gene sets revealed striking overlaps between the different cancer types with several genes including XRCC3 and RAD51B as potential candidates for further investigation." (PMID 27683114, 2016). "In addition, we found five genes with CNA losses (DMD, ARID1A, RB1, RAD51B and PTEN) that overlapped pan-cancer CNA drivers." (PMID 26429873, 2015). "Loss of the integral HR pathway components in cancers with non-BRCA HR defects due to germline or somatic mutations in PALB2, RAD51B, RAD51C, or RAD51D, or their inactivation through promoter methylation, might be the cause of olaparib susceptibility." (PMID 35741017, 2022).
cancer (continued). "The mutagenic processes result from loss of integral HR pathway components; therefore, cancers with non-BRCA HR defects, such as germline or somatic mutations in PALB2, RAD51B, RAD51C, or RAD51D, or their inactivation through promoter methylation, would also receive a positive treatment prediction." (PMID 31727117, 2019).
tumor (47 papers, 2014 to 2026). "After establishing the in vivo system in both HP5008 and 545 cells to monitor ER signaling during tumor progression, we clearly showed that the loss of RAD51B expression triggers a switch from ERα-positive to ERα-negative tumors." (PMID 41318657, 2025). "During the molecular tumor board discussion, the identified RAD51B loss-of-function mutation was recognized as the primary actionable target, conferring a “BRCAness” phenotype and predicting sensitivity to PARP inhibitors." (PMID 40963850, 2025). "We also detected progression-related alterations in RAD51B and other DNA repair pathway genes associated with the promotion of error-prone DNA repair, potentially facilitating tumor progression." (PMID 37932833, 2023). "Interestingly, a trend toward an increased NHEJ activity score upon RAD51B loss was detected across all tumor grades." (PMID 37932833, 2023). "In addition, genes including BRAF, DCTN1 and RAD51B were among the 20 tumour-related genes that were found to be mutated only in the PTCa and PTCb patients." (PMID 36686473, 2022). "Haploinsufficiency of RAD51B leads to aberrant HR repair of DNA and causes centrosome fragmentation and aneuploidy in human cells which suggests that loss of the proper biallelic expression of RAD51B may lead to chromosome instability in tumor cells." (PMID 27149063, 2016). "RAD51B, a tumor suppressor critical for homologous recombination repair (HRR), exhibited compromised function due to this truncation." (PMID 41317331, 2026). "We observed enhanced tumor growth but decreased luciferase signal after dox-induced Rad51b knockout at day 16 compared with control." (PMID 41318657, 2025). "Among these was an HNSC tumor (TCGA-4077) locus where two high-copy viral loose ends on chromosome 14 flanking an intronic region of the RAD51B gene were fused to opposite ends of the HPV-16 genome." (PMID 37945902, 2023). "In our cohort, a comprehensive tumor profile including homologous recombination genes (i.e., ATM, PALB2, RAD50, RAD51, RAD51B, RAD51C, RAD51D...) was performed for 100 cases, finding pathogenic alterations in four tumor samples, as previously reported." (PMID 35406410, 2022). "RAD51B, as a tumor suppressor gene, belongs to RAD51 protein family that is essential for DNA repair by homologous recombination." (PMID 30956756, 2019). "By detecting the expression of RAD51B in the HCC cohort and precancerous lesions, we found that RAD51B was downregulated in both tumor tissues and precancerous lesions." (PMID 30482241, 2018). "To identify novel tumor-specific promoters, we examined expression levels of Rad51 paralogs, Rad51B, Rad51C, and Rad51D as well as Rad52 in a panel of normal and tumor cell lines." (PMID 24742710, 2014). "We found that RAD51B deletion increased the tumor growth in mice." (PMID 41318657, 2025). "Dox-induced Rad51b deletion accelerated tumor growth compared to the untreated control." (PMID 41318657, 2025). "In addition to known tumor-promoting genes, e.g., c-MYC, YAP1, RAD51B, TRIB3, SLC17A9, JADE1, we found that NAPRT, encoding a key enzyme for NAD+ biosynthesis from nicotinic acid, was also suppressed in HCC cells by the BRD4 inhibitor." (PMID 35399501, 2022). "The specific HRR mutations identified in the 21 tumour samples were: BRIP1 (n = 5), CDK12 (n = 3), RAD54L (n = 2), RAD51B (n = 2), RAD54L rearr (n = 1), ATM rearr (n = 1), FANCA rearr (n = 1), FANCD2 (n = 1), FANCL rearr (n = 1), FANCL (n = 1), RAD51C (n = 1), RAD52 del (n = 1), XRCC3 rearr (n = 1)." (PMID 30353044, 2018).